PVRIG2P (PVR related immunoglobulin domain containing 2, pseudogene)
Gene: Transcribed unprocessed pseudogene on chromosome 7 (100,352,360 to 100,353,692, forward strand). Ensembl gene ENSG00000235333.
Diseases named in the same sentence as PVRIG2P in open-access papers:
PVRIG2P is named in the same sentence as 5 diseases in open-access papers, as found by Europe PMC text mining. Sharing a sentence is not in itself a finding about the gene and the disease.
PVRIG2P shares sentences with these, for which no sentence is quoted: tumor (3 papers); bladder cancer (2); cancer (1); colorectal cancer (1); renal papillary cell carcinoma (1).